JAK2 (Janus kinase 2)
Diseases named in the same sentence as JAK2 in open-access papers (continued):
Sharing a sentence is not in itself a finding about the gene and the disease.
thrombosis (continued). "In high (history of thrombosis or age >60 with JAK2 V617F)- and intermediate (age >60, no JAK2 mutation, and no history of thrombosis)-risk ET, cytoreductive therapy is mandatory to obtain both symptom relief and reduction in cardiovascular risk." (PMID 38672756, 2024). "Aspirin should not be used, or used carefully, in patients with clinically significant acquired von Willebrand syndrome or a very-low-risk score (Age ≤60, no JAK2 mutation, and no history of thrombosis)." (PMID 38672756, 2024). "It has become apparent that JAK2 V617F confer an independent risk factor for venous thrombosis, but not for arterial thrombosis in ET and PMF." (PMID 38776019, 2024). "Several lines of evidence indicate that mutations in JAK2, MPL, TET2 and ASXL1 gene and polymorphisms in several clotting factors (GPIa, GPIIa, and GPIIIa) are associated with the occurrence and prevalence of thrombosis in MPN patients." (PMID 36611455, 2023). "Therefore, the JAK2 V617F mutation should be determined in patients with MPN especially in those aged 60 years or older and with a history of previous thrombosis and leucocytosis." (PMID 36611455, 2023). "First, the small sample size of this study did not confirm that JAK2 mutation and history of previous thrombosis were independent predictors of future thrombotic events in PV patients." (PMID 37907800, 2023). "The risk of VTE was increased by 7.4-fold when the JAK2 allele burden is >20% (p = 0.004), 8.8-fold by 50% (p = 0.006) and there is a more significant risk with allele burden of >75% (p = 0.002), with mostly cases with proximal deep vein thrombosis (DVT) (p = 0.041) for allele burden of >50%." (PMID 36611455, 2023). "However, as we show in this cohort, the JAK-2 positive cases included also first-ever thrombosis cases presenting with normal blood counts." (PMID 35493844, 2022). "The order of acquisition in JAK2-mutated MPN with co-occurring mutation in TET2 impacts the disease phenotype and patients with JAK2 as first mutations have a higher risk of thrombosis and they have higher probability of presenting with PV than ET with an higher risk of thrombosis." (PMID 35562964, 2022). "The JAK-2 screening rationale was based on the accepted practice to include patients that present either with abnormal blood counts or with recurrent and/or idiopathic thrombosis." (PMID 35493844, 2022). "On multivariate analysis, JAK2 allele burden showed a non-significant trend to higher risk of venous thrombosis (HR 4.86, 95%CI: 0.9–26.3, p = 0.067)." (PMID 36042023, 2022). "Experimentation using JAK2-V617F-positive mice to investigate the role of platelets in various thrombosis models has provided heterogeneous results: In ET, the aberrant activation of the PI3 kinase/Rap1/integrin αIIbβ3 pathway leading to ex vivo platelet hypo-reactivity has been described." (PMID 35328626, 2022). "Based on these pharmacodynamic (PD) data, a b.i.d. aspirin regimen was recently recommended for patients with PV deemed at “high” thrombotic risk based on Janus Kinase 2 (JAK2) V617F mutation allelic burden, leukocytosis, age greater than 60 years, and/or previous thrombosis." (PMID 36200184, 2022). "The patients with venous thrombosis at other sites, the JAK2 rs V617F mutation was no more common than in the general population, and the frequency of the JAK2 rs V617F mutation was more strongly associated with PVT even in absence of other risk factors." (PMID 33507708, 2021). "The study concluded that the JAK2 V617F mutant allelic burden greater than 50% was significantly related to the risk of developing post-PV MF but not to the risk of developing AML or thrombosis." (PMID 34833034, 2021). "JAK2 V617F positivity or high mutant allele burden does not seem to have a clear association with survival, leukaemia transformation or risk of thrombosis." (PMID 28677265, 2017). "JAK2 positivity was shown to increase both arterial and venous thrombosis by 2-fold in ET patients." (PMID 27094255, 2016).
thrombosis (continued). "The most ambitious risk score project is the IPSET-thrombosis, which has been validated retrospectively but not prospectively, and contains age >60, thrombosis history, cardiovascular risk and JAK2 positivity." (PMID 27497846, 2016). "The JAK-2 V617F-mutation, a transversion mutation at nucleotide 1849 of JAK2, results in a valine-to-phenylalanine substitution at codon 617 and is associated with an increased risk of venous thrombosis via endothelial over-expression of the von Willebrand factor and p-selectin." (PMID 40792243, 2025). "Additionally, hematopoietic JAK2-V617F expression may promote venous thrombosis by enhancing the formation of neutrophil extracellular traps within the thrombus." (PMID 40287867, 2025). "In the entire cohort, in univariate analysis, JAK2 mutation (HR:2.3, 95% CI: 1.2–4.8, p = 0.026), elevated WBC count (>11 × 109/L) (HR: 2.1, 95% CI: 1.1–4.3, p = 0.043) and absence of splenomegaly at diagnosis (HR: 3.3, 95% CI: 1.0–11.0, p = 0.053) were associated with increased risk of thrombosis." (PMID 40074852, 2025). "The incidence rate of thrombosis in intermediate risk revised IPSET-thrombosis (aged >60 years, JAK2-negative, and no history of thrombosis) was very low regardless of the treatment administered (0.9% and 0% per year with and without cytoreduction, respectively)." (PMID 37476303, 2023). "Interestingly, in our collected data, none of the patients with PMF developed thrombosis, and none had JAK2 mutations." (PMID 36766480, 2023). "Meanwhile, the revised IPSET-t (r-IPSET-t) algorithm stratifies patients into four groups: very low risk (VLR, no risk factor), low risk (LR, JAK2 mutation), intermediate risk (IR, ≥ 60 years of age) or high risk of thrombosis (HR, history of thrombosis or ≥ 60 years of age with JAK2 mutation)." (PMID 37660316, 2023). "Anti-platelet therapy with acetylsalicylic acid (ASA) is recommended in patients > 60 years or in the presence of either the driver mutation JAK2-V617F or uncontrolled cardiovascular risk factors or a history of thrombosis provided there are no risk factors for hemorrhage." (PMID 33712866, 2021). "In addition, cytoreductive therapy was recommended in patients aged 60 years and above although not judged mandatory by Barbui et Tefferi in the absence of cardiovascular risk factors, a history of thrombosis, and JAK2 mutations." (PMID 33712866, 2021). "Patients harboring JAK2 V617F mutation were at higher risk of VTE (P = 0.024), mainly deep vein thrombosis (DVT)." (PMID 33906312, 2021). "For separate model simulations of JAK2 subgroups, the incidences of MF and thrombosis reached considerably higher levels for patients with JAK2 >50%, which might imply that possible differences in JAK2 levels across different studies could explain differences in incidence of MF and thrombosis." (PMID 32685599, 2020). "On the other hand, only 16.7% of JAK2 mutation-negative patients had thrombosis (p=0.041)." (PMID 27094255, 2016). "In ET, the JAK2 V617F mutation is present in approximately 50% of patients and is associated with higher hemoglobin levels, lower platelet counts, elevated leukocyte counts, and increased rates of venous thrombosis compared to ET patients without JAK2 mutations." (PMID 40507313, 2025). "In the 9 individuals with JAK2-mutant and incident VTE, 4 had deep vein thrombosis, 4 had pulmonary embolism, and 1 had portal vein thrombosis." (PMID 39102652, 2024). "Hence, to detect any latent MPN, screening for the JAK2 V617F mutation was recommended in patients with major idiopathic abdominal vein thrombosis who have normal blood counts, but not in patients with arterial and venous thrombosis at usual sites." (PMID 36611455, 2023). "The very low-risk group includes patients aged 60 years or younger with no history of thrombosis and wild type JAK2." (PMID 40507313, 2025).
thrombosis (continued). "Conversely, antiplatelets are avoided by physicians, mostly in cases of ET patients < 60 years who are JAK2-negative and without prior thrombosis (69.2%), who are young (<40 years of age) (50%), and CALR-mutated (23.1%)." (PMID 40094998, 2025). "Secondly, it is of the utmost importance to ascertain whether the VAF in JAK2 V617F plays a role in MPN-SVT, not only in diagnosis and prognosis, but also in achieving thrombosis-related outcomes (e.g., recanalization, recurrence)." (PMID 38338802, 2024). "In a cohort study from Czech, the JAK2 mutation was detected in 145 patients with MPN, 40 of whom had thrombosis (27.6%), which was significantly higher than those without (8.0%, p = 0.001)." (PMID 36611455, 2023). "The implication of this common practice is that in most cases of idiopathic thrombosis in patients with normal blood count JAK-2 workup is not performed routinely." (PMID 35493844, 2022). "In contrast, none of the JAK2 V617F-negative ET patients without the GCC genotype had thrombosis, and splenomegaly was frequently seen in this subset of ET patients." (PMID 22251709, 2012). "Thrombotic risk did not depend on JAK2 rs12343867, TERT rs2736100, OBFC1 rs9420907 SNV, however, we found a novel strong tendency towards statistical significance between the CC genotype miR-146a rs2431697 and thrombosis." (PMID 36242602, 2023). "The relationship of JAK2, CALR, and MPL mutations with thrombosis and splenomegaly is not clear." (PMID 35444868, 2022). "In case of a history of venous thrombosis, anti-platelet therapy usually does not suffice but systemic anticoagulation is necessary and may be combined with ASS in the presence of a JAK2 mutation or cardiovascular risk factors." (PMID 33712866, 2021). "It is important to note that probably not the JAK2 pathogenic variant itself has a causal effect on CTEPH manifestation, but its effects on increased erythrocytosis and increased risk of thrombosis may increase the likelihood of CTEPH development." (PMID 32397294, 2020). "Moreover, interesting evidence reported an increased frequency of the JAK2 haplotypeGGCC_46/1 in patients with MPN characterized by splanchnic vein thrombosis (SVT), both in the presence and absence of the JAK2 V617F mutation." (PMID 29641446, 2018). "None of the JAK2 V617F-negative ET patients without the GCC genotype had thrombosis (p = 0.0446), and splenomegaly was more frequently seen in this subset of ET patients (p = 0.0448), indicating that JAK2 V617F-negative ET without genetic variation shows a distinct clinical feature." (PMID 22251709, 2012). "However, in terms of the frequency of venous thrombosis, MPL patients had a significantly higher rate than JAK2-negative patients (p = 0.02) in addition to exhibiting microvascular symptoms in MPL patients compared with other mutations (p < 0.01)." (PMID 36611455, 2023).
melanoma (128 papers, 2010 to 2026). A malignant, usually aggressive tumor composed of atypical, neoplastic melanocytes. "Studies have demonstrated a correlation between JAK2 mutations and PD-L1 expression in both melanoma and MPNs." (PMID 40650198, 2025). "A study has depicted that loss-of-function mutations in JAK1 or JAK2 were found in two of four melanoma patients presenting with acquired resistance to anti-PD-1 therapy." (PMID 37614504, 2023). "The role of this JAK2 variant has mainly been studied for hematological cancers, but it has been identified with low frequency in melanoma as well." (PMID 36672229, 2023). "Exosomal miR-155-5p secreted by melanoma cells can induce the proangiogenic switch of cancer-associated fibroblasts (CAFs) via the SOCS1/JAK2/STAT3 pathway." (PMID 37248542, 2023). "Loss-of-function mutations in JAK1 and JAK2 are extensively reported to be the cause of ICB resistance in melanoma patients and gynecologic cancers." (PMID 37275859, 2023). "Inactivating JAK1/JAK2 mutations are detected in some tumor types (particularly melanoma), making these mutations candidates for observed ICB resistance." (PMID 34385592, 2022). "As for inactivating mutations in JAK1 or JAK2, these have been also linked to resistance to anti-PD-1 therapy in melanoma, but more research to evaluate their response to anti-PD-1 agents in CRC." (PMID 32090113, 2020). "JAK1 or JAK2 inactivating mutations have been described in melanoma patients that prevent IFN-γ signaling, PD-L1 expression, and acquired resistance to anti-PD-1 therapy." (PMID 33419311, 2020). "Loss-of-function mutations in JAK1 and JAK2 have been associated with primary and acquired resistance to PD-1 blockade in melanomas." (PMID 29082853, 2017). "Here we demonstrate that IFNγ-resistant melanoma clones with inactivating JAK1/JAK2 mutations frequently evolve in patients receiving different types of immunotherapy." (PMID 28561041, 2017). "Hyperactivation of the STAT3 pathway, a downstream target of ROS-activated JAK2 kinase signalling, is intimately linked with melanoma development and the acquisition of tumor invasiveness." (PMID 27756874, 2016). "Taken together, our data indicate that SOID-8 inhibits the JAK2/STAT3 signaling pathway in melanoma cells, associated with induction of apoptosis induced by SOID-8." (PMID 23166634, 2012). "Acquired resistance to anti-PD-1 ICI in patients with melanoma has been reported to be associated with defects in the pathways involving interferon-receptor–associated Janus kinase 1 (JAK1) or Janus kinase 2 (JAK2), as well as in the antigen-presenting protein beta-2-microglobulin (B2M)." (PMID 40236650, 2025). "For instance, a study on melanoma indicated that mutations in JAK1/JAK2 may contribute to resistance against PD-1 antibody treatments." (PMID 40650198, 2025). "Similarly, functional loss of JAK1/JAK 2 mutations has been found in melanoma samples and melanoma cell lines, which fail to respond to IFN-γ signaling and result in lack of PD-L1 expression." (PMID 35842707, 2022). "Of note, in melanoma, PD-L1/PD-L2/JAK2 amplification could be associated with durable response to immunotherapy." (PMID 31514305, 2019). "In addition, loss-of-function mutations in Janus kinase 1 (JAK1) or Janus kinase 2 (JAK2) can lead to resistance to PD-1 therapy in melanoma by blocking the IFN-γ signal." (PMID 31824840, 2019). "Functional studies undertaken by the same researchers suggested that loss of JAK2 function in melanoma cells could impairs IFN signaling, causing resistance to T cell-mediated cytotoxicity and thereby leading to recurrence of the melanoma." (PMID 31110180, 2019).
melanoma (continued). "Additionally, inactivating mutations with LOH of Janus kinase 2 (JAK2) in one relapsed melanoma patient following ICB abrogated MHC class I and peptide transporter TAP1 upregulation in response to IFN-γ." (PMID 30466478, 2018). "Furthermore, loss-of-function mutations in the upstream IFNγ-signaling regulators JAK1 and JAK2, concurrent with deletion of the wild type alleles, have been identified in two melanoma patients who failed anti-PD-1 therapy." (PMID 29977240, 2018). "Finally, we observe mutations in beta-2 microglobulin (B2M), a necessary component of antigen presentation, associated with high estimates of NK cells in melanoma, and JAK2 mutations with higher NK levels in colon cancer." (PMID 28749946, 2017). "Loss-of-function mutations in the interferon-receptor-associated Janus kinase 1 (JAK1) and/or Janus kinase 2 (JAK2) genes in melanoma and mismatch repair-deficient colon cancer have been implicated in acquired resistance, or possibly even primary resistance, to PD-1 inhibition." (PMID 28428947, 2017). "In addition, WP1066 is effective in vivo against highly malignant melanomas and leukemias that are positive for the JAK2-V617F+ mutation, which promotes constitutive JAK2 kinase activation." (PMID 24804649, 2014). "But in a separate study observed that AMF2 induces apoptosis in malignant melanoma cells as a JAK2 inhibitor." (PMID 40841966, 2025). "In BRAFV600E-positive human melanoma, activation of the JAK2/STAT3 pathway led to increased COX-2 expression, sustaining chronic inflammation and promoting tumor evasion." (PMID 39941844, 2025). "In this respect, the preferential contribution of JAK1 over JAK2 to the induction of PD-L1 by IFN-γ in melanoma cells has been reported." (PMID 40108693, 2025). "For instance, previous research has unveiled the role of the LHFPL3-AS1/miR-580-3p/STAT3 axis in promoting melanoma progression through the activation of the JAK2/STAT3 pathway." (PMID 38911376, 2024). "In a study of melanoma with acquired resistance to ICI, JAK1-mutated melanoma cell lines were resistant to both Type I and II IFN signaling, while JAK2-mutated cells were resistant to Type II IFN but responded to Type I IFN signaling." (PMID 39802951, 2024). "Overexpression and deregulation of MYC have been implicated in resistance to immunotherapy in other cancers, including melanoma and head and neck squamous cell carcinoma, through decreased IFNγ via JAK2 downregulation." (PMID 39802951, 2024). "Studies report that the transcription factor JAKs/STATs axis primarily regulates PD‐L1 expression, while JAK2 seems to play a dispensable role in melanoma." (PMID 36515567, 2023). "In our cohort, IFNγ signaling was disrupted in only 1/22 PD1 PROG melanoma, and this JAK2-mutant progressing tumor was also de-differentiated." (PMID 36934113, 2023). "At the genomic level, IFNGR has high mutation frequency of 12%, comparable with JAK1, JAK2, and IRF1, in melanoma patients resistant to anti-CTLA4 therapy." (PMID 37275859, 2023). "This compound has been described to inhibit melanoma growth via inhibition of the JAK2/STAT3 pathway." (PMID 36224606, 2022). "TQ also demonstrated synergistic effects when combined with radiation in HNSCC through inhibition of proliferation and enhanced the effect of gamma knife on apoptosis and DNA damage in B16-F10 melanoma cells by modulating the JAK2/STAT3 pathway." (PMID 35326517, 2022). "The mutation of JAK1/JAK2 results in PD-L1 depletion and insensitivity to IFN-γ, ultimately causing the primary resistance to anti-PD-1 treatment in melanoma and colorectal cancer patients." (PMID 36189283, 2022). "Consistently, it has been proposed that melanoma cell-secreted exosomal miR-155-5p can induce the proangiogenic switch of CAFs via the SOCS1/JAK2/STAT3 signaling pathway." (PMID 35443745, 2022).